SHH (sonic hedgehog signaling molecule)
Diseases named in the same sentence as SHH in open-access papers (continued):
Sharing a sentence is not in itself a finding about the gene and the disease.
tumor (519 papers, 2006 to 2026). "Elevated SHH expression, which is associated with poor tumor differentiation 44, is also observed in drug-resistant NSCLC cell lines." (PMID 41522355, 2026). "The SHH pathway, linked to pituitary embryogenesis, appears to sustain tumor stem cells and promote tumor growth, infiltration, and angiogenesis via autocrine and paracrine mechanisms." (PMID 40433410, 2025). "Transcriptomic and functional analyses revealed that TM treatment led to the decrease of GLI2 and inhibition of the SHH signaling pathway, accounting for the underlying mechanism of its anti-tumor activity." (PMID 39881254, 2025). "CD133+ cancer stem cells, a population thought to cause tumor chemoresistance, are thought to play a role in this resistance through activation of the Notch and Sonic hedgehog (SHH) signaling pathways." (PMID 40802352, 2025). "Mouse models of PDAC deficient in SHH demonstrated that Hedgehog inhibition leads to the absence of tumor stroma and the abundance of intratumoral blood vessels, yet increases tumor aggressiveness and metastasis." (PMID 40427098, 2025). "For example, stromal depletion through sonic hedgehog (SHH) loss or αSMA+ myofibroblast ablation enhances tumor aggressiveness in the background of oncogenic Kras, challenging classical views of the stroma as predominantly tumor-promoting." (PMID 40427173, 2025). "The exact cause of this phenomenon remains uncertain; however, aberrations in the SMO gene can result in anomalous stimulation of the Sonic Hedgehog (SHH) pathway, potentially causing heightened cellular proliferation and the development of tumours." (PMID 38672677, 2024). "DDX3X expression on WNT and SHH has priorly been known and is implicated in the survival, growth, and malignant potential of the tumor cells." (PMID 39160595, 2024). "Both Rab23 gene and SHH pathway have also been implicated in tumor invasion and migration of HCC through their regulation of cell growth." (PMID 37884351, 2024). "The tumor suppressor-gene PTCH1 encodes a transmembrane receptor protein for hedgehog family signaling molecules such as sonic hedgehog (SHH)." (PMID 39796697, 2024). "Although small-molecule SMO inhibitors have exhibited promising anti-tumor activity in SHH-MB, certain mutations within the SHH pathway can limit the efficacy of SMO inhibition, resulting in therapy resistance." (PMID 39107797, 2024). "Conversely, inhibiting both PI3K/Akt and SHH pathways results in tumour apoptosis and reduced growth of PTEN-deficient GBMs in experimental models, underscoring the crosstalk between these pathways." (PMID 39568072, 2024). "PTCH1 is a tumor suppressor gene encoding a large transmembrane protein that regulates the sonic hedgehog (SHH) signaling pathway." (PMID 38473071, 2024). "Murine models suggest a paracrine tumorigenesis model where β-catenin accumulating tumor cells secret senescence-associated factors, e.g., SHH, FGFs, BMPs, proinflammatory cytokines and chemokines to drive tumor growth and activate immune response." (PMID 39223689, 2024). "While SHH alone caused tumours in 15% of the mice, the combination of SHH with IGF2 and Akt increased tumour incidence to 39% and 48%, respectively." (PMID 39568072, 2024). "They revealed that the SHH pathway is frequently activated in tumor samples, suggesting a potential direct association with HCC development." (PMID 38816668, 2024). "Whilst this is a small proportion (n = 3) of total ATRT-SHH tumours (n = 65), SMARCA4 mutation does occur at a much lower rate compared to SMARCB1 in ATRT and its exclusivity to the SHH subgroup is notable." (PMID 37433987, 2023). "Previously, in PDAC, it was reported that HIF-1α activation by tumor hypoxia causes secretion of sonic hedgehog (SHH) by cancer cells, which stimulates deposition of fibrous tissue by stromal fibroblasts." (PMID 38028629, 2023). "The loss of CREBBP acts synergistically with SHH signals to enhance SHH pathway output and drive tumor growth in MB." (PMID 36937322, 2023).
tumor (continued). "SHH activated the pathway in pancreatic fibroblasts and loss of SHH resulted in a decreased number of tumor fibroblasts." (PMID 36010600, 2022). "KRAS mutations in tumor cells increases the pool of cytokines secreted (GM-CSF, G-CSF, SHH), and, therefore, are exposed to CAFs in the TME." (PMID 36612058, 2022). "Accordingly, dysregulation of SHH signaling has been implicated in the initiation and/or maintenance of different tumor types including GBM." (PMID 36010607, 2022). "The principal cause of such treatment failure was an enhanced tumor aggressiveness and metastasis due to a drastic stroma modification, e.g., increased intratumoral vascularization induced by the SHH inhibitor." (PMID 34298680, 2021). "The altered SHH signalling pathway is mainly caused by germline or somatic mutation or copy number alterations in the SHH signalling pathway, which leads to tumour development and proliferation." (PMID 34944941, 2021). "From this study, the molecular mechanism underlying how pharmacological suppression of SHH signaling inhibited tumor development in the murine CCC model remains elusive." (PMID 34948011, 2021). "PTHLH (parathyroid hormone related protein) is an important growth factor that exhibits pleiotropic effects, including tumor cell growth, death, and differentiation, which has been linked to the SHH pathway." (PMID 32316671, 2020). "This seems to be the case in BC, in which aberrant upregulation of SHH has been reported in association with progression and changes in the tumor microenviroment." (PMID 31027259, 2019). "In contrast to OPN, tumor derived SHH is associated with the classical subtype of PDA and was shown to restrain tumor growth." (PMID 31134896, 2019). "Several studies have implicated the sonic hedgehog (SHH) pathway in Gas1-mediated tumor growth inhibition." (PMID 30327548, 2018). "Subgroups 1 and 2 are associated with aberrant Wnt/β-catenin and sonic hedgehog (SHH) signaling, respectively, and all identified DDX3X mutations belonged to tumor samples of the Wnt or SHH subgroups." (PMID 29222110, 2018). "Mutations in the SHH signaling pathway, which primary cilia are known to transduce, can promote tumor growth in a fraction of GBMs." (PMID 30410731, 2018). "Oncogenic microRNAs (miRNAs) and tumor suppressor miRNAs targeting the genes encoding these signaling proteins are summarized, and the interactions between Wnt, SHH, TGFβ, and miRNAs are interpreted." (PMID 28708091, 2017). "Consistent with this role in SHH signal transduction, loss of primary cilia causes cerebellar hypoplasia and modulates the effects of other mutations on tumor formation." (PMID 29615573, 2017). "Lower expression of SHH was significantly associated with advanced tumor invasion, increased lymph node metastasis." (PMID 27039174, 2016). "Mutations in the SHH pathway suppressor Patched or alterations of other SHH pathway components result in its permanent activation and MB tumor formation." (PMID 26938241, 2016). "In vitro, higher SHH expression was associated with several tumor progression features and poorer OS in GC." (PMID 27039174, 2016). "Due to the increase in vascularity of the SHH deficient mice tumors, the authors investigated the effect of angiogenesis inhibition by administering anti-VEGF to tumor-bearing SHH deficient mice." (PMID 25352983, 2014). "Earlyclinical trials of SHH pathway inhibitors are underway, although acquired resistancehas been reported and tumours with downstream pathway mutations (e.g. GLI2, SUFU)are predicted to be insensitive to their action." (PMID 24252690, 2013). "Treatment with SHH siRNA was associated with tumor growth inhibition as compared to scrambled siRNA-treated mice." (PMID 23940460, 2013).
tumor (continued). "SHH (encoding the Sonic Hh ligand) and most of the target genes of the Hh pathway were markedly overexpressed, even in pTa low-grade tumours." (PMID 22361633, 2012). "In tumor tissue, cancer-associated fibroblasts (CAFs) are activated by paracrine stimulation of SHH signaling, which may be induced by SHH proteins released from tumor cells or CSCs." (PMID 40635786, 2025). "Further functional studies will be necessary to determine whether EWSR1 loss influences tumor evolution or SHH pathway dependence in CS." (PMID 41419593, 2025). "However, elevated SUFU permits the generation of more GLI activators, thereby rendering the SHH pathway to be activated to higher levels and exacerbating the consequence of the original tumor-driving mutations." (PMID 38358805, 2024). "Particularly mutated PTCH1 may further disinhibit SMO until SHH-independent pathway activation occurs, eventually resulting in cell cycle disruptions, uncontrolled proliferation and ultimately tumor formation." (PMID 39796697, 2024). "Moreover, primary cilia are either required for or inhibit SHH MB tumor formation depending on the underlying oncogenic event in the SHH pathway." (PMID 37726268, 2023). "Collectively, the transcriptomic changes following trametinib treatment demonstrate significant and sustained alterations in cell cycle, cell death and differentiation-related pathways, as well as genes associated with SHH pathway signaling in human and mouse SHH MB tumor cells." (PMID 37726268, 2023). "ATOH1 plays a key role in SHH-MB by mediating the transit proliferation of granule cell precursors and suppressing differentiation in response to SHH, which is secreted by Purkinje cells, MB cells, and tumor-associated astrocytes." (PMID 36291792, 2022). "In contrast to MB in children, which are located in the cerebellar midline arising from the vermis, MBs in adult patients are predominantly represented by the sonic hedgehog (SHH)-mutated tumor subtype (60–70%), which is primarily located in the cerebellar hemispheres." (PMID 35954372, 2022). "Furthermore, many reports have emphasized that the EGFR and SHH signaling pathways are also upregulated in ACPs and are associated with tumor cell migration." (PMID 34707096, 2021). "Based on such evidence, we hypothesized that a close association between CX43 and SHH pathway in promoting cell network, cell renewal and tumor microenvironment may be critical to sustain the GBM malignancy progression." (PMID 34439999, 2021). "Specifically, SHH is released by tumor cells and is detectable in serum and it was shown to correlate with higher risk of early relapse, compared to patients with low or null levels of serum SHH." (PMID 31027259, 2019). "Thus, it can be concluded that mouse models with mutations in the genes that encode four or more different parts of SHH signaling develop at least BCC-like neoplasia." (PMID 29301290, 2018). "SHh pathway inhibition suppressed stromal desmoplasia, but accelerated tumor progression of Kras-driven mice; whereas activation of SHh signaling caused stromal hyperplasia and reduced epithelial proliferation, leading to a restraint rather than a supporting effect on tumorigenesis." (PMID 28753978, 2017). "Furthermore, it was shown that EGFR- and SHH signaling pathways are also up-regulated in adaCP and associated with tumor cell migration." (PMID 26927026, 2016). "High SHH tumor expression was associated with a poor prognosis (P = 0.033)." (PMID 27039174, 2016).
tumor (continued). "Interestingly, unmodified and dnKif3a-expressing cell lines displayed differential sensitivities and pathway activation to SHH and variable tumor-associated survival following mouse xenografts." (PMID 26760767, 2016). "Additionally, Notch1 and Sonic hedgehog (SHH) are also closely associated with the differentiation of various tumor cells." (PMID 26563263, 2015). "A previous study has demonstrated that SHH signaling is activated in irradiated dying tumor cells, and that the activation of SHH in irradiated dying cells is positively associated with the stimulatory effect on living tumor cell growth." (PMID 25713298, 2015). "The SHH signaling pathway is not only implicated in normal organ development and homeostasis, stem cell maintenance and proliferation, but also in repair of normal tissue injury and tumor development." (PMID 23762282, 2013). "To examine whether SHH signaling pathway activation was associated with stimulation of tumor cell growth by dying cells, we carried out Western blot experiments with two cancer cell lines, Panc1 and HT29." (PMID 23762282, 2013). "In addition to playing a role in tumor development, the SHH signaling pathway has also been implicated in the cellular response to radiation in previous studies." (PMID 23762282, 2013). "We sought to analyze the promoter methylation status of ten putative (tumor suppressor) genes that are associated with Sonic Hedgehog (SHH), WNT signaling and (hair follicle) tumors in a large series of 112 BCC and 124 healthy control samples by methylation-specific PCR." (PMID 23284750, 2012). "MBSHH-specific mutations could interplay with SHH signaling to accelerate tumor progression." (PMID 35573667, 2022). "In addition to the WNT subgroup (10–15% of tumours), the sonic hedgehog (SHH) subgroup (~25%) is characterised by mutational aberrations in the SHH pathway (e.g., PTCH1, SUFU) and is associated with desmoplastic/nodular histology (particularly in young children) and frequent chromosome 9q deletions." (PMID 34885186, 2021). "However, upregulating SHH expression may drive TSCs into the cell cycle and increase the susceptibility of tumor cells to chemoradiotherapy." (PMID 26563263, 2015). "Suppressor of fused (SUFU), a core member of SHH signal transduction, functions as a tumour suppressor by inhibiting the activity of transcription factors glioma-associated oncogene homologue (GLI)-triggered SHH signalling pathway." (PMID 41797322, 2026). "An analysis of 50 BTC cases found overexpression of GLI1 and PTCH1 in 50% and 30% of cases, respectively, with SHH pathway overactivation detected in 50% of tumor cells." (PMID 41465387, 2025). "Activation of the Sonic Hedgehog (SHH) pathway by H. pylori infection promotes both PD‐L1 expression and tumor cell proliferation in GC, contributing to resistance against immunotherapy." (PMID 40231893, 2025). "In fact, a study concluded that cyclopamine treatment disrupts GBM tumor stem cell morphology and reduces tumor stem cell numbers by inhibiting the SHH pathway." (PMID 40802352, 2025). "Among these, the Sonic Hedgehog (SHH) pathway can become reactivated in tumorigenic cells, supporting stemness and tumor progression." (PMID 40894044, 2025). "This subgroup is commonly associated with mutations in the PTCH1, SMO, and SUFU genes, which disrupt the SHH pathway and promote tumor growth." (PMID 40868156, 2025). "Hedgehog (HH) signalling is generally activated in myCAFs, and depletion of SHH (a HH ligand) in PDAC tumours led to reduced stroma content but more aggressive cancer with increased vascularity." (PMID 39780187, 2025).
tumor (continued). "ATRT-SHH presents at a median age of 20 months as an infratentorial and/or supratentorial tumor with overexpression of sonic hedgehog (SHH) and Notch pathway components." (PMID 40052132, 2025). "We have examined how the four major molecular subtypes—WNT, SHH, Group 3, and Group 4—exhibit distinct metabolic dependencies and epigenetic regulatory patterns that govern tumor progression, therapeutic response, and prognosis." (PMID 40868156, 2025). "In contrast, SHH-subtype tumors exhibit specific DNA methylation signatures that promote SHH pathway activation, maintaining tumor cell proliferation." (PMID 40868156, 2025). "Certain myCAF (αSMA+) subpopulations have demonstrated tumor-restraining functions in some cancers when stimulated by the Sonic hedgehog (SHH)–smoothened (Smo) signaling pathway, a critical cell–cell communication system for adult tissue homeostasis." (PMID 40805183, 2025). "The same SHH-targeting mechanism was found in human nasopharyngeal cancer stemness eradication, including the arrangement of tumor spheroids." (PMID 39940882, 2025). "The Hedgehog (SHH) pathway exerts control over numerous aspects of cancer cell “stemness,” including their capacity to proliferate and instigate tumor formation." (PMID 40136652, 2025). "By reducing cholesterol levels, statins can effectively suppress the hedgehog pathway, thereby inhibiting tumor growth and proliferation in SHH-driven MB." (PMID 40977747, 2025). "Our work delineates cellular and transcriptional changes that lead to greatly accellerated tumor growth when Pten is mosaicly removed in GCPs that have activated SHH-signaling due to expression of SmoM2." (PMID 40766638, 2025). "Intriguingly, deleting SHH in murine models reduced tumor interstitium, but these SHH-deleted tumors exhibited heightened proliferative ability and aggressiveness." (PMID 38540204, 2024). "Overall, our study indicate that reducing Rab23 gene expression inhibit tumor cell growth and promoted apoptosis in vivo by downregulating the SHH signaling pathway." (PMID 37884351, 2024). "A greater emphasis should be placed on understanding the interplay between SHH signalling and other molecular pathways in CNS tumours including aspects of the tumour immune microenvironment." (PMID 39568072, 2024). "Tumor cells upregulate SHH, leading to the activation of the surrounding stroma and tumor progression." (PMID 38672552, 2024). "Receptor Smoothened (SMO, SE = 4.8) activation by SHH ligands promotes tumor growth, while SHH/SMO pathway inhibition by the SMO antagonist, LDE225, in CAFs impairs tumor growth." (PMID 38892190, 2024). "In CCA, TAMs can promote tumor progression through various pathways, such as the SHH/GLI2/TGF-β1 pathway and the aPKCγ/CCL5 pathway, as previously summarized." (PMID 39290697, 2024). "This latest, is often characterized by activation of Sonic Hedgehog (SHH) signalling, with overexpression of Gli1 and Gli2 that are responsible for the generation of an immunosuppressive tumour microenvironment." (PMID 38886736, 2024). "We further investigated the intratumoral heterogeneity of SHH, Group 3, and Group 4 datasets (17 patients) by isolating tumor cells from immune cells and stroma and analyzing them separately." (PMID 39659836, 2024). "Taken together, these data provide evidence that simultaneous inhibition of DNMT1 and SMO synergistically inhibits SHH-MB tumor growth specifically by blocking SHH pathway output." (PMID 39107797, 2024). "The tumor cell heterogeneity, identified by scRNA-seq for SHH inhibitor response, can explain the clinical drug resistance and relapse after targeted inhibitor therapy." (PMID 38355808, 2024). "Recent evidence suggests the involvement of Sonic Hedgehog (SHH) in the induction of anti-inflammatory M2-like macrophage phenotypes within tumor microenvironments." (PMID 38898530, 2024). "The tumor specimens included three molecular subtypes: SHH-activated (78.6%), WNT-activated (10.7%), and Group 4 (10.7%)." (PMID 39518048, 2024).